TNF (tumor necrosis factor)
Diseases named in the same sentence as TNF in open-access papers (continued):
Sharing a sentence is not in itself a finding about the gene and the disease.
infection (continued). "Intracellular infection of wild-type THP1 and THP1.MR1+ cell lines induced expression of tumor necrosis factor (TNF) by human MR1-5-OP-RU tetramer+ MAIT cells." (PMID 30135490, 2018). "Our findings demonstrate that both infection with P. berghei ANKA and gonadectomy trigger a cerebral sex dimorphic mRNA expression pattern of the cytokines IL-1β, TNF-α, IFN-γ, and IL-2." (PMID 30515051, 2018). "After infection of μBS by ZIKV-BR and ZIKV-UG, upregulation of TNF-α, IL6, IL1b, and CCL2 was observed when compared with BS." (PMID 30619100, 2018). "A comparison between MPI cells and BMDM was also performed, showing that 8 h after infection with live bacteria, MPI cells were secreting more TNF-α, comparable amounts of IL-6 and less IL-1β than BMDM, at all the MOI tested." (PMID 29593716, 2018). "C1q complement/tumor necrosis factor (TNF)—related protein (CTRP) family comprises of 15 proteins that posses important implications in energy homeostasis, infection and inflammation." (PMID 30557342, 2018). "At day 6 post infection, depletion of CD4 T cells resulted in significantly reduced frequencies of IFN-γ+ and TNF-α+ ILC1s." (PMID 29623077, 2018). "Three pro-inflammatory cytokines, namely tumor necrosis factor (TNF), interleukin-1β (IL-1β) and interleukin-6 (IL-6) play a pivotal role in the initial response of the innate immune system to injury or infection." (PMID 30233566, 2018). "Some studies have demonstrated the role of the flagellin of P. aeruginosa in induction of IL-6 and TNFα or CXCL8 during mouse infections." (PMID 30070169, 2018). "Concentrations of TNF-α, IFN-γ, IL-17A, and IL-22 rose sharply in the milk of UI goats when infection was out of control." (PMID 30045763, 2018). "It has been reported that the inflammation is a physiological phenomenon on responding the injury, stress and infection, and the inflammatory mediators of iNOS, COX-2, IL-1β, TNF-α and IL-6 can be increased when ALD occurred clinically." (PMID 29765084, 2018). "Infection of C57BL/6 mice that lack an expression of TNF with L. major BNI results in a progressive course of disease and visceralization while B6.WT mice contain the infection and recover spontaneously." (PMID 29403488, 2018). "In the αβ T cell compartment, reductions in IFN-γ- and TNF-α-producing CD4+ and CD8+ T cells were observed after 6 days of P. yoelii 17XNL infection." (PMID 30619302, 2018). "Expression of IL-6 and TNF-α are a potential indicators of severe respiratory viral infection, such as SARS and human infection by avian influenza viruses." (PMID 29566060, 2018). "Infection of epithelial cells by strains ATCC 17978 and PAO1 showed that IL-6, tumor necrosis factor alpha (TNF-α), and IL-10 levels were similar for hypoxia and normoxia at 2 and 24 h postinfection." (PMID 30082478, 2018). "Several reports suggest that CpG-DNA pre-treatment within 72 h before infection induces cytokine expression, including IL-6, IL-12, IFN-γ, and TNF-α, which contribute to host defense." (PMID 30390012, 2018). "Compared to ST6, infection with ST1 led initially to higher levels of IL-1β and TNF-α in blood and more profound neuropathological damage." (PMID 30193592, 2018). "In cell culture studies, the infection of 75A.stop mutants based on equivalent PFU led to an acceleration in viral gene expression in fibroblast cells and enhanced TNFα release and increased cytotoxicity in infected BMDMs." (PMID 29390024, 2018). "Second, the characterization of this response revealed a high degree of polyfunctionality including IFN-γ+TNF-α+IL-2+ triple positive CD8+ T-cells, which often correlates with better protection against infection." (PMID 30364187, 2018). "Oral epithelial cells were shown to express various cytokines and chemokines such as TNF-α, IL-1β, and CCL2 that were upregulated upon infection in our study." (PMID 29967614, 2018).
infection (continued). "After infection with the IB004 strain, TNF-α levels were below the limit of detection in all mice, similar to results obtained in uninfected mice." (PMID 29638177, 2018). "In HepG2 with infection of ATCC 43251 + 0.5 μmol/L DPI treatment, the expression of TNF‐α is decreased about 26.7% and the expression of IL‐1β is increased about 29.4% comparing with that of without DPI treatment." (PMID 30258592, 2018). "Further, serum levels of interleukin (IL)-2, interferon γ, tumor necrosis factor (TNF)-α, IL-12p70, IL-22, IL-17A, and IL-5 increased significantly after infection." (PMID 30564216, 2018). "In HIV-1-infected humanized mice, however, we found that HAART starting during early phase of infection (4wpi) rescued both ILC1 number and functions in IFN-γ and TNF-α production." (PMID 29304123, 2018). "During the quiescent period, serum cytokine, chemokine and CAM levels declined; however, TNF-α, IFN-γ and MCP-1 levels then increased on day 7 post-infection in parallel with the appearance of neurological signs in mice with melioidosis." (PMID 30206252, 2018). "In an in vivo mouse intratracheal infection model, specific inhibition of NE by sivelestat significantly upregulated BALF TNF levels, suggesting that mouse NE cleaves mouse TNF." (PMID 29922273, 2018). "The classical activation of macrophages occurs following an injury or infection by agents such as microbial products or pro-inflammatory cytokines including bacterial lipopolysaccharides (LPS), interferon-γ (IFN-γ) or tumor necrosis factor-α (TNF-α)." (PMID 29707159, 2018). "As revealed by pulmonary cytokine detection, the increase in pulmonary TNF-α, IL-1β, IL-6, and IL-8 levels was more severe in the lean mice than in the DIO mice after infection." (PMID 30250258, 2018). "The UdLAMPs of both Ureaplasma stimulated the gene expression of IL-1β, TNF-α, TLR2 and TLR4 after 6 and 12 h following infection in macrophages." (PMID 30050519, 2018). "In this work, we report that both infection with P. berghei ANKA and gonadectomy triggered a sexually dimorphic cerebral mRNA expression pattern of the cytokines IL-1β, TNF-α, IFN-γ, and IL-2." (PMID 30515051, 2018). "Spearman rank correlations between age, gender, IFN-γ, TNF-α, IL-10, IL-17A, ratio IFN-γ/IL-10, and exposure time in the infection place less or equal -and longer- than 90 days." (PMID 30186774, 2018). "So, we repeated the infection experiment explained above with supernatants from gB-CAR T cells plus/minus neutralizing antibodies against IFN-γ and TNF." (PMID 29422056, 2018). "Changes in gene expression of TNF-α, TLR-22, and NF-κB in the control were in line with the pre-challenge levels in the treatment groups, which were better protected from the infection." (PMID 30237797, 2018). "In contrast, the infection induces a potent immune response in mice’s skin mediated by CD4+ T cells with an effector phenotype that produces high levels of IFN-γ and TNFα." (PMID 29946313, 2018). "In T. cruzi-infected muMT mice, TNF-producing cells are mostly CD4+ T cells, implying that B cells condition the CD4+ T cell response during the infection." (PMID 29209313, 2017). "It is important to reiterate that bdMφ upregulate a full range of cytokines via TLR-dependent pathways, including TNFα, IL12 and IL1β53, 54, 55, which contribute to protective immunity during infection, or immunisation with BCG." (PMID 28382943, 2017). "Differential changes in the expression of CCL19, CCL20, IL-8, IL-15, and Trail/TNF (ligand) superfamily members TNFSF10 and TNFSF15 in DT40 cells were also observed at different time points after vvIBDV infection." (PMID 28086922, 2017). "TNF was secreted at a slower rate than MCP-1 but, by 24 h post-infection, was detected at ∼2500 ρg/ml." (PMID 28856457, 2017). "Changes in mesothelial cell gene expression of CCL5, TLR4, TNF, ZFP36, EDN1 and ITLN1 1 hour after infection with S. epidermidis." (PMID 28542390, 2017).
infection (continued). "Third, influenza A virus (Hkx31; 105 PFU per mouse) infection in mice in vivo for 24 h resulted in greater increases in lung IFN-β, IL-1β, IL-6, and TNF-α mRNA, as well as serum and lung IFN-β protein in NOX2−/y mice." (PMID 28701733, 2017). "TH1-cytokines (TNF-α, IFN-γ, IL-12p70) and TH2-cytokines (IL-4, IL-10, IL-13) were measured 8 weeks after initial infection." (PMID 28542175, 2017). "Thirty days post infection, chitosan treatment resulted in MPO, MCP-1, TNF-α, IL-12p70 and IL-4 levels falling to control values, but IL-6, IL-10 and TGF-β were elevated." (PMID 29156562, 2017). "By the time infection progresses, T-helper (TH1) cell with its cytokine secretions, such as tumor necrosis factor-alpha (TNF-α) and interferon-gamma (IFN-γ), propagates the adaptive limb of the immunity." (PMID 28228760, 2017). ", 2005), interleukin (IL)‐1α, IL‐6, tumor necrosis factor (TNF)‐α, and interferon (IFN)‐γ levels were significantly upregulated upon infection of ND mice, as were many others." (PMID 27794208, 2017). "Previous results suggested that apoptosis of PBMO after infection with E. coli occurred via internalization of TNFR1, and indicated a relevant role for TNF-α." (PMID 28793310, 2017). "IL-6 is a pleiotropic cytokine secreted by a variety of cells in response to various stimuli, such as infections and other cytokines, including IL-1β, interferon gamma (IFN-γ), and TNF-α." (PMID 29233145, 2017). "Severe or recurrent infections by atypical/non-pathogenic mycobacteria and other intra-macrophagic infections, including salmonellosis are characteristic in patients with Mendelian Susceptibility to Mycobacterial Disease and in patients treated with anti-TNF-α." (PMID 28983301, 2017). "After challenge with B. microti, the levels of cytokines including IL-17, IL-4, IL-6, IL-10, IL-12p70, G-CSF, IFN-γ, TNF-α, IL-2, GM-CSF, MCP-1, MIP-1α, MIP-1β, and MIP-2 in the serum of the BMSA vaccinated group changed as infection progressed." (PMID 29312230, 2017). "Despite the fact that measurements occurred two days after the initial infection, the alginate + LESB58 mice had significant increases in MCP-1, KC, IL-6, and TNF-α in the lungs and in KC and IL-6 in the serum." (PMID 29107983, 2017). "Similar to norovirus challenge infections, the natural infection reported here transiently increased serum IFN-γ, IL-2, IL-6 and TNF-α concentrations." (PMID 28815218, 2017). "Overall, BMM derived from CLEC5A−/− mice showed reduced TNF-α and IP-10 but increased IFN-α compared to the WT mice after infection with the VNHA,NA virus or treatment with PIC." (PMID 27795434, 2017). "DCs also secrete tumor necrosis factor (TNF)-α and the chemokine CXCL8 which recruit neutrophils to the infection site." (PMID 29358941, 2017). "Compared to 129sv mice, the levels of TNF-α, IL-1α, and MIP-1α were 76%, 58%, and 42% higher in Alox5−/− mice at the 1st day post-infection." (PMID 29247243, 2017). "There was a significant reduction in TNF-α, IL-6, and CXCL10 transcripts during Opal524R infection at this time point." (PMID 29138302, 2017). "The infection can be controlled with the formation of a granuloma, where the CD4+ cells and Tumor necrosis factor alpha (TNF-α) macrophages are key factors for reactivation surveillance." (PMID 28086756, 2017). "Animals infected with the NM showed a decreased level of pro-inflammatory cytokines TNF-α, IFN-ɣ and IL-21 throughout the course of the infection and higher levels of IL-10." (PMID 28650996, 2017). "However, the risk of infection with the hTNF-K treatment could not be easily studied in the TTG mice because antihuman TNF-α antibodies are usually species-specific and do not cross-react with murine TNF-α." (PMID 29184553, 2017). "H5N1 virus induced higher levels of TNF-α and IFN-α in the infected M-Mφ, but the levels of chemokines (IP-10 and MCP-1) were comparable after infection with H1N1, H5N1, or H7N9 viruses." (PMID 27795434, 2017).
infection (continued). "It is interesting that despite the induction of proinflammatory cytokines early after infection, CMV suppresses TNF-α and IL-1β signaling pathways at late times, demonstrating unique adaptation capacities that enable virus persistence within the host." (PMID 28241080, 2017). "LPS is a potent inductor of pro-inflammatory factors such as TNF-α and IL-1β as well as IL-8 and CXCL family chemokines that reproduce the effect of an infection." (PMID 28486961, 2017). "Combination of detecting level of TNF-α/IL-4 balance, CSS antigen and IgG concentration is good tool for appropriate diagnosis of such infection." (PMID 28717322, 2017). "In this study, we found that binding of TNF to its receptor, TNFR-1 induces a remarkable ROS production in Brucella-infected macrophages at late infection through upregulating the function of mitochondrial chain." (PMID 29062811, 2017). "NH1125B, as compared to NH1067B, induced IL-6 earlier during infection and induced greater levels of CCL5 and TNFα transcripts in the MDM of the 2 donors (#67 and #68) presented." (PMID 28877226, 2017). "Among all recombinant viruses, we found that the PB2 mutant with K at 627 induced higher level of TNF-α, IP-10, MCP-1 and MIP-1α at both 3 and 6 days post-infection when compared to the wild type 627E virus and the other two PB2 mutants." (PMID 28539661, 2017). "CD4 T cells and cytokines derived from these cells, such as IFN-γ and TNF, have pleiotropic antiviral effects and are essential for the control of viremia in LCMV Cl13 infection." (PMID 28747914, 2017). "The expression of pro-inflammatory cytokines (TNF-α and IL-6) and chemokines (KC and MCP-1) was strongly reduced in the presence of LH-C from 4 to 6 days post infection." (PMID 28235408, 2017). "Since prolonged anti TNF-α or IL-17 therapies bear the risk of severe infections or development of metaplastic malignancies, only short-term treatment with combined anti-IL-17/anti-TNF-α antibodies might be qualified for the treatment of infection-triggered exacerbation of AAI." (PMID 29184554, 2017). "In vivo, after G81007 infection, GLY treatment reduced clinical score and messenger RNA (mRNA) expression of IL-1β, TNF-α, CXCL2 and HMGB1." (PMID 29064403, 2017). "The NF-κB pathway is involved in the expression of several genes of the immune and inflammation response to the infection such as IFNβ, CXCL2 and TNF." (PMID 29084252, 2017). "To establish a link between PumA interaction with UBAP1 and the ability of PumA to reduce TNFα‐dependent signalling (Fig EV5A), we analysed the levels of TNFR1 during infection." (PMID 28483816, 2017). "As demonstrated in both the murine TB model and in humans, TNF-α promotes the formation of mature granulomas and like IFN-γ, also activates infected macrophages, which, at least in mice, contain infection via induction of iNOS and autophagy [reviewed in Ref." (PMID 29051764, 2017). "We here show that infection with M. catarrhalis exacerbates HDM-triggered AAI mainly by an IL-17- and TNF-α-dependent inflammatory response." (PMID 29184554, 2017). "The control and clearance of this intracellular pathogen rely on the induction of several cytokines during infection, such as IL-12, IFN-γ, or TNF." (PMID 28584007, 2017). "After 24 h of infection, cells infected with the Rv2029c-overexpressing BCG exhibited markedly higher expression of TNF-α and IL-6 than those infected with BCG or BCG-pMV261." (PMID 29204139, 2017). "The use of recombinant rabies viruses further indicates that this mechanism leads to the control of IFNβ, TNF and CXCL2 expression during the infection and a high pathogenicity profile in rabies virus infected mice." (PMID 29084252, 2017). "We confirmed that TNF-α, TNF-β, TWEAK and LIGHT increased native HCV J6/JFH infection of polarized HepG2 cells and observed a significant increase in viral RNA 48 h post-infection." (PMID 27983476, 2017).
infection (continued). "Compared to Mock infection, strain SE2472 infection strongly increased the mRNA levels of inflammatory cytokines including IFN-γ, IL-1β, MIP-2, IL-33, IL-17, IL-22, TNFα, etc.." (PMID 29208934, 2017). "In patients and mice, EV-A71 infection enhances the expression of IL-1β, IFN-γ, and TNF-α, which can induce IL-6 expression." (PMID 29233145, 2017). "Type I IFNs, IFN-γ, and pro-inflammatory cytokines, such as interleukin (IL)-1, IL-6, IL-8, IL-12, and tumor necrosis factor-alpha (TNF-α), have been shown to be upregulated in lung tissue and lung lavage after experimental infection of pigs with Swine IV." (PMID 28484702, 2017). "We found that the levels of IL-1α, INF-γ, TNF-α, MCP-1, and IL-6 in the lungs post infection were significantly different between mice recolonized with microbiota from alcohol-fed and pair-fed microbiota." (PMID 28604843, 2017). "To confirm the decrease in inflammatory cell types during the peak of infection in NSC61610-treated mice, we measured the mRNA expression of inflammatory markers, IFNα, TNFα and MCP1, in the lungs of infected mice." (PMID 28270815, 2017). "Based on previous evidences on the immune modulating properties of PE_PGRS33, two pro-inflammatory cytokines, TNF-α and IL-1β, were evaluated by performing a cytometric bead array (CBA) assay on supernatants collected at 72 h from MDMs infection." (PMID 28484686, 2017). "TNF-α and CCL4 (MIP-1β) continued to be produced to significantly lower levels during Opal524R infection." (PMID 29138302, 2017). "We reduced the innate immunity functional cluster to 32 genes that were exclusively regulated by TNF-α, which was the cytokine produced at highest levels after LMWT infection of microglia." (PMID 28903312, 2017). "Immunization prior to infection induced PmpG-specific CD4 cells in the iLN that produced significantly more IFN-γ only producing cells, multiple cytokine producing cells (IFN-γ, TNFα, and IL-17) and a central memory subset." (PMID 28106821, 2017). "gambiense field isolate, FoB cells are retained, which coincided with reduced production of TNF and IFN-γ pro-inflammatory cytokines during the acute stage of infection compared to T. brucei and T. congolense infections." (PMID 28596768, 2017). "We next measured pro-inflammatory mediators in splenic tissue by ELISA and observed significant increases in IL-6, CXCL1(KC), IFN-γ, TNF-α, CCL2 (MCP-1), and MMP-3 levels after infection." (PMID 28874800, 2017). "We did note reductions in both IL-6 and IL-17, and to a lesser extent TNFα in the BAL fluid of infected IL-36R-/- mice and IL-36γ-/- mice at 24 h post infection, as compared to WT mice." (PMID 29166668, 2017). "There is a significant increase in whole brain and hippocampal TNFα mRNA, an increase in protein expression of TNFα, and an increase in the ratio of TNFR1:TNFR2 expression in the hippocampus as a consequence of TMEV infection." (PMID 28497109, 2017). "There was a significant decrease in the concentrations of TNF-α, IL-6, IL-8, and CCL2 present in the vaginal washes following the Us2 mutant infection compared with HSV-2 infected mice." (PMID 28827540, 2017). "To test the contribution of TNFα to bacterial killing by CD4+IFNγ-/- T cells we isolated naïve and immune CD4+ T cells from R. typhi-infected BALB/c IFNγ-/- mice on day 7 post infection and incubated these cells with R. typhi-infected macrophages in vitro." (PMID 28222146, 2017). "Honey stimulates monocytes (MM6 cells) to secrete cytokines, tumor necrosis factor alpha (TNF-α) and IL-1 and IL-6, which triggers the immune reaction to infection." (PMID 28127573, 2017). "In the initial 2–4 weeks after infection, under the stimulation of migrating schistosomula, the host showed Th1 type (IFN-γ, TNF) response." (PMID 28646891, 2017).